MDM2 (MDM2 proto-oncogene)
Diseases named in the same sentence as MDM2 in open-access papers (continued):
Sharing a sentence is not in itself a finding about the gene and the disease.
breast carcinoma (continued). "It will be of interest to further investigate whether it is possible for an interaction between MDM2 SNP309 and obesity-associated metabolic syndromes to affect breast cancer by assessing a larger Taiwanese population." (PMID 19144119, 2009). "However, a recent study showed that, in women whose breast cancers expressed high levels of ER, those having the MDM2 SNP309 G/G genotype showed earlier age of onset than those with the T/T genotype." (PMID 17537232, 2007). "Interestingly, aberrant splicing between direct repeat sequences with potential cryptic splice sites and without mutations in selected parts of the gene has been described also for the MDM2 oncogene in breast cancer." (PMID 18044981, 2007). "In breast cancer, 20q13 and MDM2 amplifications seem to define subsets of aggressive tumours." (PMID 8980401, 1996). "While GATA3, ESR1, PIK3CA, FOXA1, FOXO3, and RB1 protein abundances were not significantly reduced in GATA3mut breast cancers, the expression of genes associated with MDM2 function and phosphorylation of genes associated with ERK signaling and aggressive phenotypes were impacted." (PMID 40439821, 2025). "In this study, we investigate the MDM2 polymorphisms SNP309, SNP285 and del1518 for potential impact on hematopoietic recovery, focusing on neutrophil counts during neoadjuvant chemotherapy treatment with sequential monotherapy of epirubicin and docetaxel in patients with primary breast cancer." (PMID 39979836, 2025). "Therefore, elevating the expression level of S100A6 in breast cancer cells can not only promote the degradation of the oncoprotein MDM2 and inactivate some cancer progression pathways, but also lower the occurrence of chemoresistance, achieving better therapeutic effects." (PMID 37217945, 2023). "In addition, clonogenic assay, WST-1 assay, and flow cytometry of apoptosis and the cell cycle were performed and a xenograft model was established to evaluate the effects of the S100A6/MDM2 interaction on growth and paclitaxel-induced chemosensitivity of breast cancer." (PMID 37217945, 2023). "Interestingly, that the recombinant, dual-target MDM2/MDMX inhibitor could reverse doxorubicin resistance via the activation of the TAB1/TAK1/p38 MAPK cascade in breast cancer cells is consistent with our result." (PMID 35335125, 2022). "To rule out the possibility that the differential sensitivity was derived from different genetic backgrounds of breast cancer cell lines, we asked whether overexpressing the GATA3 p.D335Gfs mutation in GATA3-wild-type cells would induce hypersensitivity against MDM2 inhibition." (PMID 35440675, 2022). "The results showed that ECT2 deletion associated growth retardation of breast cancer cells could be reverted, to certain extent, by forced expression of MDM2 or USP7/wt, but not USP7/C223S." (PMID 32929379, 2020). "Finally, we performed FKBP12 silence or transfection in MDA-MB-468 breast cancer cells to confirm whether FKBP12 regulates MDM2 expression and confers sensitivity to chemotherapy." (PMID 31428819, 2019).
breast carcinoma (continued). "Whether MDM2 influences other process of breast cancer metastasis requires further exploration." (PMID 27184007, 2016). "Our results demonstrate the therapeutic potential of targeting NFAT1-MDM2 pathway and provide new insights into MDM2 targeting strategies, suggesting that InuA may be a novel therapeutic agent for the treatment and prevention of human breast cancer." (PMID 27105525, 2016). "Therefore, as enthusiasm for the preclinical development of novel MDM4/MDM2 inhibitors builds, we propose that these future agents may show utility in combination with hormonal therapies for the treatment of MDM4/MDM2-driven breast cancers." (PMID 26909605, 2016). "Thus, InuA is a novel NFAT1 and MDM2 dual targeting agent and may be a clinical candidate for breast cancer therapy." (PMID 27105525, 2016). "Interestingly, HER2 and MDM2 are the most popular targets for treating breast cancer." (PMID 27410227, 2016). "Stratifying according to MDM2 SNP309 status (SNP309TT, SNP309TG, and SNP309GG) we found the MDM4 SNP34091CC genotype (recessive model) to be significantly associated with reduced risk of breast cancer among patients carrying the SNP309GG genotype (OR = 0.41; 95% CI = 0.21–0.82)." (PMID 26471763, 2015). "We demonstrated that the MDM2-overexpressing and MDM2-knockdown cells were less sensitive to the compound, showing resistance to apoptosis and cell cycle arrest, thus supporting the importance of MDM2 inhibition in the anti-breast cancer activities of 25-OCH3-PPD." (PMID 22911819, 2012). "Therefore, in ERα+ breast cancer Mdm2 may antagonize multiple proliferative checkpoints in a way reminiscent of viral oncogenes." (PMID 21223569, 2011). "If one only studies the effects on median onset age of breast cancer in BRCA 1/2 patients the effect is small indeed, yet we also studied effects of MDM2 polymorphysm on survival in this group and here our results suggests a more profound role for the MDM2 SNP309 polymorphism." (PMID 19226467, 2009).
breast carcinoma (continued). "In conclusion, within this Scottish population the MDM2 309 polymorphism was found to associate with high grade cancers with greater nodal involvement and by implication poorer prognosis, but had no impact on the age of diagnosis of breast cancer." (PMID 18828900, 2008). "The initial editing predictions for MDM2, GINS1, and F11R, obtained from the TCGA breast cancer patient dataset was experimentally validated." (PMID 40381037, 2025). "The present study investigated the antitumor effects of MA242, a novel MDM2 and NFAT1 inhibitor, in breast cancer models." (PMID 40046748, 2025). "We confirmed A-to-I(G) editing in the 3’UTRs of MDM2 (Mouse Double Minute 2 homolog), GINS1 (GINS Complex Subunit 1), and F11R (Junctional Adhesion Molecule A) in breast cancer cells." (PMID 40381037, 2025). "Men with ER-positive/HER2-negative breast cancer had more frequent alterations in GATA3, MDM2, CDK4, BRCA2 genes as compared with FBC patients of the same subtype." (PMID 39049124, 2024). "Multiple signaling pathways are involved, and MDM2 upregulates EMT-related transcription factors through the B-Raf signaling pathway or induces EMT by enhancing Snail expression, promoting breast cancer progression." (PMID 38741108, 2024). "An oncogene pathway known to promote breast cancer metastasis in MDA-MB-231 xenografts is that of Mouse Double Minute 2 and 4 (MDM2 and MDM4, also known as MDMX)." (PMID 39766093, 2024). "Based on the database of patients with breast cancer (BRCA) from The Cancer Genome Atlas (TCGA), we observed the effect of USP7, MDM2 and DICER mRNA expression levels on the overall survival of patients." (PMID 37867415, 2024). "Inulanolide A underwent both in vitro and in vivo anticancer experiments, demonstrating its dual inhibitory effects on MDM2 and NFAT1 in breast cancer cells." (PMID 39764218, 2024). "Other oncogenes that can raise tRNA expression include MDM2, CCND and PIK3CA, all of which are sometimes amplified in breast cancers." (PMID 37509247, 2023). "miR-29b-3p overexpression reduced the stemness of lung and breast cancer cells in 3D culture, improving their radiosensitivity, and its radiation targets CND2 and MDM2 were identified." (PMID 37569824, 2023). "miR-383-3p and -5p enhanced the apoptosis and UV sensitivity of breast cancer cells, and their radiation targets CRYAB, CCND2, GATA3, NUCKS1, MAP3K20, and MDM2 were identified, while ATR is targeted by miR-383-5p." (PMID 37569824, 2023). "In both breast cancer cells and xenograft model, S100A6 suppressed the tumor growth and enhanced its sensitivity to paclitaxel, which were dependent on MDM2 inhibition." (PMID 37217945, 2023). "Consistent with this, MDM2 overexpression has been found to enhance the expression of EMT markers, such as ZEB1, via the B‐Raf signaling pathway in glioma, lung cancer, and breast cancer cells." (PMID 37138218, 2023). "In a recent study, after the treatment with gossypol, the binding between the MDM2 protein and VEGF mRNA was disrupted in breast cancer cells." (PMID 38098026, 2023). "We show that inhibition of MDM2 is synthetically lethal in GATA3-mutant and GATA3-depleted breast cancer cells." (PMID 35440675, 2022).
breast carcinoma (continued). "To clarify the regulatory role of ZLM-7 in the 14-3-3 sigma/MDM2 axis, we examined the action of ZLM-7 treatment in a breast cancer xenograft mouse model." (PMID 35890172, 2022). "Our results present MDM2 as a therapeutic target in the substantial cohort of ER-positive, GATA3-mutant breast cancer patients." (PMID 35440675, 2022). "Furthermore, our findings suggest that GATA3 mutations may drive resistance to hormonal therapy by upregulating the PI3K/Akt/mTOR pathway, suggesting that inhibition of MDM2 may help overcome the resistance to PI3K/Akt/mTOR inhibition and/or to endocrine therapy in GATA3-deficient breast cancer." (PMID 35440675, 2022). "IGF2-targeting and MDM2-targeting drugs have been in clinical trials for other tumor types, and CDK4/6 inhibitors are already approved for patients with breast cancer." (PMID 34680217, 2021). "High expression of MDM2 in our cohort with high Ki67; also in cases with Her2/neu overexpression known with predictable poor prognosis in the absence of target therapy suggest MDM2 may be associated with aggressive biological behaviour in our breast cancer cases." (PMID 34695137, 2021). "We sought to determine the antitumor efficacy of the combination of ALRN-6924, a dual inhibitor of MDM2/MDMX, with chemotherapy in ER+ breast cancer models." (PMID 33663585, 2021). "It has been demonstrated that overexpression or amplification of MDM2 and MDM4 genes are common in many malignancies, including breast cancer." (PMID 33669778, 2021). "Combinatorial inhibition of MDM2 and WIP1 enhanced tumor growth-inhibitory and cytotoxic activity of MDM2 inhibitors in melanoma, neuroblastoma and breast cancer." (PMID 33917342, 2021). "Analyzing the TCGA breast cancer database, we discovered that patients with the HER2 cancer subtype and overexpression of MDM2 exhibited decreased post-treatment survival." (PMID 34572735, 2021).
breast carcinoma (continued). "When compared to a set of randomly selected PBMCs, ClearCell Polaris captured cells showed elevated expression of breast cancer-specific markers BRCA1 and MDM2 (p-value < 0.05)." (PMID 32331451, 2020). "As JapA analogs, LinA and InuA also suppress breast cancer growth both in vitro and in vivo, and these effects are dependent on their inhibition of NFAT1 and MDM2." (PMID 32397368, 2020). "Overexpression of MDM2 protein has been shown in WDLPS and DDLPS, estrogen receptor positive (ER+) breast cancer, and multiple myeloma." (PMID 31359240, 2020). "In the only other breast cancer PDX experiments so far reported, another MDM2 inhibitor MI-77301 was effective at reducing tumour growth of two fulvestrant-resistant PDX models." (PMID 32787886, 2020). "We only evaluated MDM2/MDMX and TAB1 expression by IHC and collected the clinicopathological characteristics of 70 breast cancer patients in order to explore the correlations between MDM2/MDMX and TAB1 expression levels." (PMID 31892970, 2020). "MDM2 induces a significant enhancement in ERα-mediating gene expression and estrogen responsiveness through interactions with ERα in MCF-7 and ZR-75 breast cancer cells." (PMID 33987175, 2020). "Among the most amplified genes, we find the oncogenes SOX2, EGFR, and MDM2, and also a noncoding gene, PVT1, the most amplified gene in breast cancer, with proven but as-of-yet uncharacterized proto-oncogenic effects." (PMID 31379928, 2019). "We showed that SNPs in the MDM2 and MDMX genes affect at least in part the onset and progression of breast cancer dependent on the ER-status." (PMID 30956778, 2019). "Expression of MDM2 and MDMX occurs in estrogen receptor α-positive (ERα+) breast cancer and triple-negative breast cancer (TNBC)." (PMID 30642351, 2019). "In the present study, we confirmed that MDM2 provokes CTC formation from TNBC and report for the first time that MDMX expression also plays an active role in the production of breast cancer CTCs." (PMID 30642351, 2019). "To better understand the role of MDM2 and MDMX in breast cancer metastasis, we compared the biological outcomes of knocking them down in the highly metastatic triple-negative claudin-low MDA-MB-231 cells." (PMID 30642351, 2019). "Inhibition of Mdm2 in a dose- and time-dependent manner was observed in XWL-1-48 treatment breast cancer." (PMID 30176902, 2018).